RNVU1-34 (RNA, variant U1 small nuclear 34)
Synonyms: U1A7; RNU1-85P
Gene: Small nuclear RNA gene on chromosome 17 (58,679,527 to 58,679,690, reverse strand). Ensembl gene ENSG00000200997.
Gene Ontology:
Molecular function: pre-mRNA 5'-splice site binding
Biological process: mRNA 5'-splice site recognition
Cellular component: U1 snRNP
Homologues: Orthologues: chimpanzee U1 (95% identical), guinea pig U1 (69% identical), mouse Gm23099 (63% identical), rat U1 (63% identical), rat U1 (62% identical), dog U1 (62% identical). Paralogues in human: RNU1-1 (80% identical), RNU1-2 (80% identical), RNU1-27P (80% identical), RNU1-28P (80% identical), RNU1-3 (80% identical), RNU1-4 (80% identical), RNU1-67P (80% identical), RNVU1-18 (80% identical), RNVU1-29 (80% identical), RNVU1-31 (80% identical), U1 (80% identical), RNU1-89P (79% identical), and 134 more.